IL10 (interleukin 10)
Diseases named in the same sentence as IL10 in open-access papers (continued):
Sharing a sentence is not in itself a finding about the gene and the disease.
gastric cancer (continued). "CD14+ tumor-infiltrating macrophages expressing IL-10 have been found and enriched in gastric cancer patients to facilitate immune evasion." (PMID 40244064, 2025). "Tumor-associated mesenchymal stem cells promote immunosuppression in gastric cancer, often through the modulation of cytokines such as IL-6 and IL-10." (PMID 40723172, 2025). "Foxp3, IL-10, and TGF-β1 exhibit significant co-expression in gastric cancer and are strongly associated with the presence of tumor-infiltrating immune cells." (PMID 41438510, 2025). "Microbiota-derived butyrate is capable to reverse the immunosuppressive factors PD-L1 and IL-10 in patients with gastric cancer." (PMID 39985099, 2025). "In gastric cancer, IL-10 and TGF-β1 family molecules are significantly and concurrently upregulated in tumor tissues." (PMID 41438510, 2025). "In gastric cancer, cyclase-associated protein 2 (CAP2) bound to RACK1 and activated the SRC/FAK/ERK signaling pathway, leading to IL-4 and IL10 secretion, and M2 macrophage polarization." (PMID 38315284, 2024). "This is due to the activation of a c‐mesenchymal epithelial transition protein/STAT3 signalling pathway by IL‐10 to promote the malignant behaviour of gastric cancer cells." (PMID 38506082, 2024). "Several studies indicate increased IL-10-producing Bregs correlate with poor prognosis in gastric cancer patients." (PMID 38279997, 2024). "For example, IL-10 expressed by TAMs was significantly elevated in the tissues and sera of patients with gastric cancer, inducing immunosuppression by regulating the c-Met/STAT3 signaling pathway." (PMID 39840050, 2024). "CD19+CD24hiCD38hi cells in gastric cancer are the primary source of IL-10 and can significantly inhibit the secretion of IFN-γ and TNF-α by CD4+ T cells." (PMID 39840050, 2024). "It has been reported that exogenous addition of IL‐10 directly to gastric cancer cells can promote the proliferation of gastric cancer cells." (PMID 38506082, 2024). "We aim to explore the pertinence of gastric cancer and SNP of interleukin 10–819 by meta-analysis via five statistical models." (PMID 38365575, 2024). "In another study, human gastric cancer patient tumour MDSCs suppressed T cells ex vivo via IL-10, resulting in a decrease in CD4+ T cell production of IL-2 and IFNγ consistent with impaired effector function." (PMID 38464388, 2024). "This study suggests that IL-10 819 gene polymorphism may be a genetic biomarker of gastric cancer, and clinical detection of gene mutation typing can provide scientific theoretical basis to further reveal the biological mechanism of the prognosis of gastric cancer." (PMID 38365575, 2024). "When analyzing the prognostic impact of TAM subgroups expressing IL-10 in patients with gastric cancer, it was found that those with high IL-10 expression had a poorer prognosis and reduced responsiveness to adoptive cell therapy." (PMID 39840050, 2024). "Within this context, RNA-sequencing analysis in gastric cancer uncovered a link between macrophage-derived IL-10 and the activation of c-MET/STAT3 signaling pathways." (PMID 39664377, 2024). "In the allelic model, there was significant correlation between gastric cancer and IL-10 819 (OR = 3.96%, 95%CI: 3.28 to 3.78)." (PMID 38365575, 2024). "This indicates that STAT3 indirectly affects IL-10’s influence on the proliferation, invasion, and migration of gastric cancer cells." (PMID 39840050, 2024). "The neutralizing antibodies against IL4 and IL10 also reduced the upregulation of CD86+ macrophages induced by the overexpression of CDK5RAP3 in gastric cancer cells." (PMID 35999359, 2023). "In gastric cancer, similar to Th2 cells, macrophages can also secrete interleukin-10 (IL-10) and participate in immunosuppression." (PMID 36980973, 2023). "Rescue studies have shown that neutralizing antibodies to IL4 and IL10 can attenuate the upregulation of CD206+ macrophages induced by gastric cancer cells with low CDK5RAP3 expression." (PMID 35999359, 2023).
gastric cancer (continued). "The levels of IL4 and IL10 were significantly reduced in gastric cancer cells overexpressing CDK5RAP3." (PMID 35999359, 2023). "DC-10s is a subset of tolerogenic DCs which express high levels of HLA-G and secrete IL-10 and IL-6 in peripheral blood of patients with gastric cancer." (PMID 36053326, 2023). "AGS cells, gastric cancer cell line, were cultured with IL-10 and measured cell death and cytokine secretion." (PMID 37946227, 2023). "In gastric cancer, IL-6 induces the differentiation of M2 macrophages and promotes the secretion of tumor-promoting cytokines, such as IL-10 and TGF-β, by M2 macrophages, thus facilitating tumor growth and tumor metastasis." (PMID 35701829, 2022). "Information from clinical samples has proved that high expressions of IL-1β, IL-12, and IL-10 in macrophages or in plasma indicate poor progression of stomach cancer." (PMID 35382168, 2022). "Several studies have demonstrated that IL-6-, IL-8-, IL-10-, and IL-33 mediated pathways are involved in the invasion and metastasis of gastric cancer." (PMID 35368661, 2022). "The production of suppressive cytokine IL-10 in H. pylori-infected gastric cancer patients is elevated and thus results in a decreased cytotoxic anti-tumor T-cell response in the gastric mucosa, thereby contributing to gastric carcinogenesis." (PMID 35795038, 2022). "The intracellular interleukin (IL)-10 and IL-12 status on monocytes in patients with advanced stomach cancer were significantly increased compared with those in patients with early disease or in healthy individuals." (PMID 35382168, 2022). "All these results indicate the significant role of IL-1β, IL-12, and IL-10 in the tumor microenvironment in stomach cancer." (PMID 35382168, 2022). "For example, IL-10 plays a key role on the regulation of several genes in gastric cancer cells involved in cell proliferation and migration." (PMID 36009404, 2022). "The pro-inflammatory cytokines IL-1β, TNF, and IL-6 can induce the transition of EMT in head and neck cancers and anti-inflammatory cytokine IL-10 can lead to tumor cell proliferation through an induction of STAT3 activation in gastric cancer cells." (PMID 35283421, 2022). "On the basis of ARP and PARP associated with SNPs of gastric cancer, the top three for ARP were 53.91% (NAT2, rs1799929), 53.05% (NAT2 phenotype), and 42.85% (IL-10, rs1800896)." (PMID 34491229, 2021). "Unfortunately, few recent studies have investigated the effects of IL-10 expression specifically in relation to gastric cancer." (PMID 34944729, 2021). "Since upregulated WTAP expressions have been revealed to be significantly associated with immunosuppression in malignancies like human hepatocarcinoma and gastric cancer, we also examined the mRNA levels of mouse immunosuppressive cytokine IL-10 in our model." (PMID 34081626, 2021). "A study by Luo and Wu found that LYC treatment led to significant increases in serum IL-10 levels in rats with gastric cancer." (PMID 34827896, 2021). "Increased as well as decreased levels of IL-4 and IL-10 have been reported in esophageal and gastric cancers and their prognostic value remains uncertain." (PMID 32298379, 2020). "The result show that gastric cancer derived exosomes stimulate secretion of immune suppressive cytokine IL-10 by CD8+ T cells." (PMID 32901082, 2020). "High IL6/IL10 ratio in H. pylori-infected patients indicated that pro-inflammatory cytokines play a fundamental role in gastric cancer development." (PMID 33569347, 2020). "In contrast, extracellular vesicles levels of IL-10 levels were found to be reduced in gastric cancer." (PMID 33046133, 2020). "Despite insufficient data on disturbance of Th17/Treg balance in cancers, previous reports determined the induction of Th17 producing IL-10 cells in vivo, in vitro, and in gastric cancer patients." (PMID 33426090, 2020).
gastric cancer (continued). "H. felis infection is associated with reduced levels of interleukin-1β and tumor necrosis factor-α and increased level of interleukin-10, leading to the expression of key gastric mucosal cytokines and possibly gastric cancer." (PMID 32546214, 2020). "Our study indicated that these host immunological feature and analysis of SNPs in the IL-10 promoter can be used to follow up after endoscopic resection of early gastric cancer." (PMID 30792753, 2019). "In this study, we analyzed the IL-10 SNPs and IgG subclass responses to the bacteria in patients with early gastric cancer and recurrent gastric cancer." (PMID 30792753, 2019). "It is possible that in this tumor type, as in esophageal and gastric cancers, that immunosuppressive IL10-expressing plasma cells were present and inhibited the anti-tumor T cell response." (PMID 29899747, 2018). "The − 592 (C/A) SNP has been linked to overexpression of IL-10 and associated with the risk of developing Non-Hodgkin Lymphoma of B cells (NHL-B) even in other pathologies, including gastric cancer." (PMID 30526523, 2018). "In further Mendelian randomization analysis, the predicted OR for 10 pg/mL increment in IL-10 was 1.14 (95%CI: 1.01–16.99) in gastric cancer." (PMID 26886630, 2016). "With this in mind, we employed the classical Mendelian randomization method in this meta-analysis and found that patients with 10 pg/mL increment in circulating IL-10 were 1.14 times more likely to develop gastric cancer." (PMID 26886630, 2016). "In this study, we determined that increased CD19+CD24hiCD38hi Bregs in gastric cancer possess a robust immune regulatory capacity to produce IL-10 and TGF-β1." (PMID 26378021, 2015). "IL-10+ B cells were also analyzed in PBMCs, peritumoral tissues, and tumor tissues of gastric cancer patients using flow cytometry." (PMID 26378021, 2015). "Patients with gastric cancer (GC) have significantly higher IL-6 levels, and lower IL-8 and IL-10 concentrations, in comparison to controls and patients with other gastric neoplasms." (PMID 26486258, 2015). "We found that, among the analyzed ILs, IL-6, IL-8, and IL-10 levels were significantly different among patients with gastric cancer in comparison to both healthy individuals and patients with other types of gastric malignancies." (PMID 26486258, 2015). "There were genomic predispositions of SNPs in the ITGA5, ITGB1, IL-10 and COX-2 genes in the children of GCA, who are considered to be a risk group of gastric cancer after H. pylori infection." (PMID 25884934, 2015). "Our results demonstrate that CD19+CD24hiCD38hi B cell subsets possess a robust immune regulatory capacity to produce IL-10 in gastric cancer, which is consistent with a previous report in SLE and includes most CD5+CD1dhi B cells." (PMID 26378021, 2015). "The differences between IL-10− and IL-10+ were also compared both in healthy control PBMCs and gastric cancer lesions." (PMID 26378021, 2015). "A reduced risk of gastric cancer has been found in carriers of IL1B-31C of Asian origin and in carriers of IL10-592A (including all ethnic groups)." (PMID 24892619, 2013). "IL-10 is one of the immunosuppressive cytokines, which is elevated in blood in advanced gastric cancer." (PMID 24116074, 2013). "The presence of various proinflammatory IL-10 genotypes, TNF-α, IL1B and the IL-1 receptor antagonist increases the risk of development of gastric carcinoma." (PMID 23995914, 2013). "The results showed that as compared with healthy individuals, the maturation marker CD40 in MDDCs, IL-17A expression from T cells, and IL-10 expression from MDDCs were significantly lower in gastric cancer patients." (PMID 22526791, 2012). "We also examined the regulatory signal pathways in IL-10 cytokine production after H. pylori stimulation and compared the cytokine profiles of healthy individuals and gastric cancer patients after stimulation with H. pylori." (PMID 22526791, 2012).
gastric cancer (continued). "In gastric cancer, the notable upregulation of IL-10 and TGF-β1 family molecules plays a crucial role in forming an immunosuppressive microenvironment, offering valuable molecular insights for identifying immunotherapy targets and developing combined intervention strategies." (PMID 41438510, 2025). "This is consistent with the results of previous studies that added GLP that 400 mg/kg GLP reduced serum levels of IL-1β and IL-6 in diabetic rats, and 800 mg/kg GLP reduced serum IL-6 and TNF-α levels and increased serum IL-2, IL-4, and IL-10 levels in rats with gastric cancer." (PMID 39457856, 2024). "For example, Sarah, Jie Liu, Su SPbelieve that IL-10 819 gene polymorphism is not related to the risk of gastric cancer." (PMID 38365575, 2024). "IL-10 knockdown resulted in induction of the lytic cycle and enhanced tumor cell destruction in both gastric cancer and LCLs when performed in combination with doxorubicin, suggesting that this tendency towards increased IL-10 expression can be targeted to treat EBV-associated tumors." (PMID 38179040, 2023). "Similarly, in the inflammatory microenvironment of gastric cancer, Helicobacter pylori activates downstream inflammatory factors, like IL-6, IL-10, and COX-2, through TLRs (mainly TLR2 and TLR4), thus initiating a series of inflammatory responses." (PMID 37153547, 2023). "H. pylori infection downregulates its expression in gastric cancer cells and promotes the release of cytokines IL-6, IL-10, and VEGF via the JAK2-STAT3 signaling, and thus induces the maturation of dendritic cells and the reduction in the number of CD4+ and CD8+ T cells." (PMID 35795038, 2022). "The small sample bias and the short follow-up times may explain these differences, and further studies about Breg cells and IL-10 in gastric cancer are needed." (PMID 36339942, 2022). "Our study illustrated that DLL3 in stomach cancer could induce IL-1β, IL-12, and IL-10 secretion of macrophages via up-regulating IL-33." (PMID 35382168, 2022). "In terms of gastric cancer, the level of circulating IL-10 was shown to be directly dependent on the gastric cancer stage, therefore influencing the prognosis of these patients since it stimulates angiogenesis and suppresses immune responses that enable tumor progression." (PMID 35884067, 2022). "Moreover, the serum IL-6 and TNFα levels were decreased, and the serum IL-2, IL-4 and IL-10 levels were increased in gastric cancer mice after tea polysaccharides treatment." (PMID 36505461, 2022). "In MNNG gastric cancer rat model, administration of 50, 100 or 150 mg/kg body weight of lycopene caused an increment in antioxidant enzymes as expected (SOD, CAT, GSH-Px) and increment in cytokines (IL-2, IL-4, IL-10, TNF-α) and antibodies (IgG, IgA, IgM)." (PMID 34202203, 2021). "While it was shown that G-CSF is highly expressed in human gastric and colon cancers and promote carcinoma cell proliferation and migration, its strong association with IL-10 upon metastasis among gastric cancer patients has not been explored until this work." (PMID 32216812, 2020). "Conversely, in gastric cancers increased levels of both serum IL-10 and IL-4 have been reported." (PMID 32298379, 2020). "The results demonstrate that the immune suppressive gene FOXP3 and IL-10 were highly expressed in CD8+ T cells after exposed to exosomes from gastric cancer cells, which suggest that exosomes from gastric cancer are required to promote an immunosuppresive phenotype." (PMID 32901082, 2020). "Likewise, an unfavorable prognosis and higher plasma level of IL-8, IL-10 levels was also observed in the presence of higher PLR levels (≥160) in gastric cancer patients." (PMID 29742685, 2018). "The determination of IL-10 level was performed in 13 patients with gastric carcinoma." (PMID 30526523, 2018). "Likewise, IL-10 has been shown to induce the expansion of Tregs in peripheral lymphoid organs in gastric cancer patients." (PMID 28261223, 2017).
gastric cancer (continued). "Indeed, we found that values of IL-6/IL-8 and IL-6/IL-10 ratios were significantly higher in patients with gastric cancer than in both other examined groups, whereas mean IL-8/IL-10 values were comparable between all examined groups." (PMID 26486258, 2015). "IL-10-819 TT genotype is not statistically associated with the overall reduced gastric cancer susceptibility in persons with H. pylori infection compared with controls without H. pylori infection." (PMID 22436502, 2012). "Whether lower IL-10 production in gastric cancer patients than healthy controls results from the presence of immature DC or impaired intracellular signaling pathways merits evaluation in further work." (PMID 22526791, 2012). "IL-10 -819 TT genotype is not reversely associated with non-cardia or cardia subtype gastric cancer susceptibility." (PMID 22436502, 2012). "Furthermore, IL-10 expression was significantly lower in MDDCs from gastric cancer patients than in MDDCs from healthy individuals." (PMID 22526791, 2012). "The anti-inflammatory effects of FFKSIL may be related to IgA, IgM, IgG, IL-6 and TNF-α production and IL-2, IL-4 and IL-10 reduction in gastric cancer rats." (PMID 22728348, 2012). "IL-10-819 TT genotype is not statistically associated with gastric cancer susceptibility in persons infected with H. pylori." (PMID 22436502, 2012). "We also examined the association between IL10 genetic variants and the risk of gastric cancer after stratifying noncardia gastric cancer by stage (data not shown)." (PMID 22235320, 2012). "We genotyped three promoter polymorphisms (-1082A>G, -819T>C, and -592 A>C) of IL10 in a case-control study of 495 noncardia gastric cancer patients and 495 sex- and age-matched healthy controls." (PMID 22235320, 2012). "IL-10 -819 TT genotype seems to be more protective from gastric cancer in Asians." (PMID 22436502, 2012). "Next, we investigated the effects of H. pylori infection status on the association between IL10 genetic variants and the risk of noncardia gastric cancer." (PMID 22235320, 2012). "We also examined the effects of smoking on the association between IL10 genetic variants and the risk of noncardia gastric cancer." (PMID 22235320, 2012). "However, IL-10 expression was significantly lower in MDDCs from gastric cancer patients as compared with healthy controls." (PMID 22526791, 2012). "In the previous study on the molecular mechanism of the action of Elian granules on precancerous lesions of gastric cancer through network pharmacology, we found that the active components of Elian granules can regulate the activation factors of M2-type macrophages, such as IL-4 and IL-10." (PMID 37291549, 2023). "IL-35-producing B cells were also elevated in the peripheral blood of gastric cancer (GC) patients and were responsible for the accumulation of immune suppressive Treg cells, MDSCs, IL-10-producing B cells and CD14+ monocytes." (PMID 33418929, 2021). "The combined genotype such as ITGA5-1160/ITGB1-1949/ITGB1 + 31804 as T/A/C carriers and COX-2-1195/IL-10-592 as G-carrier/AA, or even more specifically combined with RUNX3 + 492/TFF2-308, may thus serve as a host factor to identify the risk group of gastric cancer for an early H. pylori eradication." (PMID 25884934, 2015). "Moreover, IL-6 and STAT3 downstream signals such as IL-10 and VEGF were reduced in patients after removal of gastric cancer as compared to pre-operation, this was associated with recovery of T lymphocytes and NK cells in peripheral circulation in these patients." (PMID 24116074, 2013). "Indeed, gastric cancer cells themselves can secrete IL-10, which may explain its reduction in patients after removal of gastric cancer as compared to pre-operation in the present study." (PMID 24116074, 2013). "The IL10-819C and -592C alleles were found to have complete linkage disequilibrium, and all three IL10 polymorphisms were associated with an increased risk of intestinal-type noncardia gastric cancer." (PMID 22235320, 2012).